BAX (BCL2 associated X, apoptosis regulator)
Diseases named in the same sentence as BAX in open-access papers (continued):
Sharing a sentence is not in itself a finding about the gene and the disease.
glaucoma (13 papers, 2005 to 2024). Increased pressure in the eyeball due to obstruction of the outflow of aqueous humor. "Activation of the BAX protein has been shown to be the determining step in the intrinsic apoptotic pathway that causes RGCs to die in glaucoma." (PMID 34376637, 2021). "As in the glaucoma, BAX deficiency protected retinal ganglion cells after axon injury by optic nerve crush." (PMID 16103918, 2005). "Together with our finding that complete BAX deficiency delays IOP elevation in a glaucoma setting, these results strongly support further investigation of apoptotic pathways and effects of antiapoptotic drugs on IOP in human glaucoma." (PMID 16103918, 2005). "DBA/2J mice deficient in the proapoptotic molecule BCL2-associated X protein (BAX) were used to investigate the roles of BAX-mediated cell death pathways in glaucoma." (PMID 16103918, 2005). "Their data also suggest that the BAX gene is a candidate to modulate glaucoma susceptibility." (PMID 16103918, 2005). "To provide insight to the nature and location of the damaging insults that occur in glaucoma, we compared the effects of BAX deficiency on RGC death in inherited glaucoma to RGC death induced by either direct optic nerve injury or excitotoxicity (all in the genetically uniform DBA/2J strain)." (PMID 16103918, 2005). "Additionally, we compared the effects of BAX deficiency on the glaucoma to its effects on retinal ganglion cell death due to two insults that are proposed to participate in glaucoma." (PMID 16103918, 2005). "Thus, it is possible that either low-expressing or low-activity alleles of BAX may affect glaucoma susceptibility both by limiting and/or delaying IOP elevation and by directly protecting RGCs from damaging effects of harmfully high IOP." (PMID 16103918, 2005). "Finally, our data suggest that reducing BAX levels in the retina may retard the rate of vision loss in glaucoma." (PMID 16103918, 2005). "RGC apoptosis in glaucoma involves a cascade of pro-apoptotic factors, including BAX, a member of the BCL-2 family of endogenous transcription factors that regulate the delicate balance between cell survival and death." (PMID 39456800, 2024). "In the WT mice, molecular analysis of the right retina with microbead-induced glaucoma revealed increased expression of the following genes (mean ± SD): BAX 1.44 ± 0.58 fold; TNFα, 1.38 ± 0.32 fold; CD45, 5.45 ± 0.25 fold; STAT3, 2.15 ± 0.72 fold." (PMID 37111243, 2023). "In summary, the molecular analysis revealed that the induction of glaucoma by microbead injection results in an increase in the expression levels of markers of damage (BAX, CD45, and TNFα) in the retina and optic nerve." (PMID 37111243, 2023). "Deficiency of BAX gives long-term protection of RGC soma and slows axonal loss in glaucoma mouse models." (PMID 24736625, 2014). "Considering the protection we demonstrate in this mouse model, it is worth assessing BAX pathways as important targets for new treatments in human glaucoma." (PMID 16103918, 2005). "BAX-mediated unwanted cell death is known to induce various degenerative diseases including Alzheimer’s disease, Parkinson disease, Amyotrophic Lateral Sclerosis, Huntington disease, ischemia-reperfusion tissue injuries, and glaucoma." (PMID 38891043, 2024). "In previous studies BAX was correlated with neurodegeneration in glaucoma." (PMID 23071659, 2012). "In situations where BAX is important, pharmacologically suppressing BAX activity may significantly slow the progression of glaucoma." (PMID 16103918, 2005). "BAX is the first molecule shown to be completely necessary for RGC death in any glaucoma." (PMID 16103918, 2005). "In contrast, our experiments show that BAX is required for RGC death in glaucoma." (PMID 16103918, 2005).
glaucoma (continued). "In addition, we also quantitatively analyzed both groups for the expression of apoptosis-related (BAD, BAX, BCL2L10, and XIAP) and autophagy-associated (HAX1 and Beclin-1) marker proteins, since both signaling cascades are supposed to be highly involved in the molecular pathogenesis of glaucoma." (PMID 36313990, 2022). "It is known that BAX is an important proapoptotic molecule in retinal development, after RGC axonal injury, and in glaucoma." (PMID 21762490, 2011). "Gene therapy targeting RGCs to prevent BAX activation in a glaucoma model has not yet been performed, making this a clinically relevant approach that can also be tested in wild-type mice without the developmental defects associated with Bax deletion." (PMID 39456800, 2024). "Gene therapy targeted directly to RGCs to prevent BAX activation in a glaucoma model has never been attempted." (PMID 34376637, 2021). "BAX, the pro-apoptotic BCL2 member required for the normal death of RGC during development, has been identified as a major mediator of RGC death in glaucoma." (PMID 24736625, 2014). "BAX is required for retinal ganglion cell death in an inherited glaucoma; however, it is not required for retinal ganglion cell axon degeneration." (PMID 16103918, 2005). "Thus, there is no reasonable explanation for the finding of prolonged survival of RGCs that have no axons other than that BAX is a necessary RGC-intrinsic molecule for apoptosis in this glaucoma model." (PMID 16103918, 2005).
chronic lymphocytic leukemia (12 papers, 2014 to 2025). "The comparative analysis of the frequencies of polymorphic variants of locus‐248G> A of BAX gene in chronic lymphocytic leukemia (CLL) patients revealed a significant difference in GG‐genotype among the CLL patients and the control group." (PMID 26744613, 2016). "Recently, a SNP located within the 5′-untranslated region of the BAX promoter, G-248A (rs4645878), was reported to be associated with both reduced expression of BAX and altered susceptibility to chronic lymphocytic leukemia." (PMID 24672785, 2014). "Moreover, BAX-mutated CH has been shown to arise after the treatment with a BCL-2 inhibitor, venetoclax, in patients with chronic lymphocytic leukemia (CLL), strongly reflecting the evolutionary dynamics in response to targeting antiapoptotic proteins." (PMID 39352380, 2024). "Since toxicity could be induced without any sign of cellular damage, in some experiments cell clonogenic capacity and BAX (BCL2 associated X protein) and BCL2 (B-cell CLL/lymphoma 2) gene expression ratio were also evaluated." (PMID 28882181, 2017). "The products of BCL2 and its homologs, including BAX and BCL2L12, are implicated in chronic lymphocytic leukemia (CLL)." (PMID 37424436, 2023). "Our data suggest a multifaceted role of BAX and BCL2L12 circRNAs in B‐cell CLL." (PMID 37424436, 2023).
acute lymphoblastic leukemia (11 papers, 2007 to 2024). Leukemia with an acute onset, characterized by the presence of lymphoblasts in the bone marrow and the peripheral blood. "Approximately 21% of lines of human hematopoietic malignancies possessed mutations in BAX, perhaps most commonly in the acute lymphoblastic leukemia subset." (PMID 17868464, 2007). "B-cell lymphoma-2 (BCL2) has been identified in acute lymphoblastic leukaemia and has later been shown to inhibit apoptosis, while BCL2-associated X (BAX) is a well-known proapoptotic factor." (PMID 37525208, 2023). "By inducing pre-apoptotic BCL-2 proteins, including BAX proteins, GC exacerbates the expression of the anti-apoptotic BCL-2 protein by causing caspase cascade and inducing apoptosis in the cell line of lymphoblastic leukaemia." (PMID 32102534, 2020). "GC induces activation of caspase cascade and induces apoptosis in the cell line of lymphoblastic leukemia by increasing in BAX protein and decreasing the BCL2 protein." (PMID 32102534, 2020). "In Jurkat acute lymphoid leukaemia cells, there was a significant increase in the expression of BAD, BAX, and CYT c genes and proteins, as well as CASP-9 and CASP-3 genes when compared to the vehicle control (P ≤ 0.05)." (PMID 35614109, 2022). "The aim of the current research was defined to probe the effect of sub-toxic prednisolone dose on the level of promoter methylation and gene expression of BAX and BCL2 in the T acute lymphoblastic leukemia cell line (CCRF-CEM)." (PMID 32102534, 2020). "This study defined to probe the apoptotic effect of sub-toxic dose of prednisolone on the expression and level of promoter methylation of BAX and BCL2 genes in CCRF-CEM acute lymphoblastic leukemia cells." (PMID 32102534, 2020).
heart failure (11 papers, 2012 to 2025). Inability of the heart to pump blood at an adequate rate to meet tissue metabolic requirements. "Activation of this pathway caused BAX, and caspase-2 to be upregulated and activated, causing CM apoptosis and heart failure." (PMID 35246252, 2022). "Astragalus also reduced expression of BAX in heart failure rats and increase Bcl-2 expression by Astragaloside IV, a main component in Astragalus." (PMID 25342960, 2014). "It has been suggested that BAX is upregulated and may play a role in cardiomyocyte apoptosis in heart failure due to volume overload." (PMID 22862895, 2012). "In a mouse model of DOX-induced heart failure, the levels of BCL2 were downregulated, and the levels of BAX and cleaved caspase-3 became elevated." (PMID 35246252, 2022). "As such, Latif and colleagues found the pro-apoptotic BCL2 family members BAX and BAK upregulated in patients with heart failure." (PMID 28666417, 2017). "On molecular level, myocardial ANKRD1 and serum adiponectin correlated with low BAX/BCL-2 ratios, indicative of antiapoptotic tissue propensity observed during the worsening of heart failure." (PMID 25961010, 2015). "However, conditional deletion of MCL-1 in mice induced heart failure in a BAK- and BAX-dependent process, raising concerns for cardiac toxicity with MCL-1 inhibitors." (PMID 34065859, 2021).
oral cancer (11 papers, 2015 to 2025). "Overall, this study highlights the promising role of naringin as a pro-apoptotic and cytotoxic phytochemical regulating the gene expression of Bcl-2, TGF-β, SMAD2, TNFα, NFκB, BAD, BAX, and caspase-3, thereby treating oral cancer." (PMID 39156270, 2024). "In summary, this research emphasizes the potential of naringin as a cytotoxic and pro-apoptotic phytochemical that modulates the expression of Bcl-2, TGF-β, SMAD2, TNFα, NFκB, BAD, BAX, and caspase-3 genes, ultimately aiding the treatment of oral cancer." (PMID 39156270, 2024). "This contrasts with the common view of cancer as anti-apoptotic and anti-senescence, but it is consistent with previous studies that reported a high expression of BAX at the mRNA and protein level and a high degree of apoptosis in oral cancer." (PMID 38188288, 2023). "The current study offers in vitro experimental studies on a human cell line model evidence of the therapeutic impact of hesperidin on inhibiting oral cancer cells by inhibiting pro-inflammatory signaling molecules and activating BAX (pro-apoptotic protein) signaling." (PMID 38435153, 2024). "Intriguingly, we noticed that CLU interacts with both LC3 and BAX, presumably forming a trimeric complex (BAX-CLU-LC3) in cisplatin-treated cells recruiting a phagophore to generate a mitophagosome around damaged mitochondria for successful mitophagy leading to enhanced oral cancer cell survival." (PMID 38447939, 2024). "In oral cancer cells, we found that treatment with naringin markedly reduced Bcl-2 and increased the expression of the anti-apoptotic genes BAD, BAX, and caspase-3." (PMID 39156270, 2024). "In oral cancer, dysregulation of apoptosis-related genes such as BCL2, which inhibits apoptosis, and BAX, which promotes apoptosis, can disrupt the delicate balance between cell proliferation and cell death, leading to uncontrolled tumor growth." (PMID 38907185, 2024). "The genes BAD, BAX, caspase-3, and Bcl-2 are thought to be markers specific to KB1 oral cancer cells." (PMID 39156270, 2024).
thyroid cancer (11 papers, 2015 to 2025). "An IHC analysis was performed to identify alterations in PCNA and cell apoptosis-associated protein (BAX) levels in thyroid cancer tissues." (PMID 39459033, 2024). "The most frequently associated genes with thyroid cancer found on PubMed were BAX, XRCC1, XRCC3, XPO5, IL-10, BRAF, RET, and K-RAS." (PMID 37211566, 2023). "Auranofin induced apoptosis in thyroid cancer cells through the upregulation of BAX and cleaved PARP and downregulation of Bcl-2." (PMID 39459033, 2024). "For example, GPX3 is a Category 2 protein where suppression directly correlates with promotion of metastasis in human thyroid cancer, and the Category 1 protein, BAX has been reported to be upregulated in relation to papillary thyroid cancer." (PMID 32092871, 2020). "TBX15 acts as an anti-apoptotic factor in thyroid cancer by inhibiting the expression of proapoptotic BAX and increasing the expression of antiapoptotic BCL2 and BCL-XL regulators." (PMID 33447348, 2020). "In thyroid tissues, an elevated expression of BAX was demonstrated in thyroid carcinoma compared to adenoma." (PMID 27042160, 2016). "In addition, sesquiterpene lactones, such as alantolactone and isoalantolactone, from Inula helenium have been reported to induce intrinsic apoptosis in thyroid cancer and oral squamous carcinoma cells through ROS generation, BAX/BCL-2 ratio modulation, and caspase-3 activation." (PMID 40864793, 2025). "In thyroid cancer cells, oncogene activation prevented TGF-ß/SMAD-dependent p27 repression and CDK2/SMAD3 phosphorylation, leading to p65 up-regulation, which repressed BAX, induced cyclin D1 and promoted TGF-ß-dependent growth." (PMID 37954148, 2023).
Alzheimer disease (10 papers, 2017 to 2024). A progressive, neurodegenerative disease characterized by loss of function and death of nerve cells in several areas of the brain leading to loss of cognitive function such as memory and language. "Exercise is reported to exert its therapeutic influence on Alzheimer's disease through the targeting FoxO1(N. Zhao, Xia, & Xu, 2021) and by reducing brain damage by increasing Bcl‐2 and decreasing caspase‐3 and BAX expression in cerebral ischemia." (PMID 36448290, 2023). "In Aβ1–40-induced Alzheimer’s disease (AD), ginsenoside Rb1 inhibits the expression of BAX and caspase-3 in the hippocampus and increases the expression of BCl-2, thereby regulating the neuronal cell death pathway and preventing AD." (PMID 37686071, 2023). "We have also analysed the interaction between BAX and BID, providing molecular evidence on the inverse comorbidity between cancer and Alzheimer’s diseases by means of changes in the pathways associated with apoptosis." (PMID 28740175, 2017). "Similarly to our studies, simultaneous increase in anti-apoptotic BCL2 and pro-apoptotic BAX was observed during prenatal exposure to cocaine and cellular models of stroke and Alzheimer’s disease." (PMID 39771121, 2024). "Moreover, PaPE-1 normalized the Aβ-induced loss of mitochondrial membrane potential and restored the BAX/BCL2 ratio, suggesting that the anti-Alzheimer’s disease (AD) capacity of PaPE-1 particularly relies on inhibition of the mitochondrial apoptotic pathway." (PMID 34797527, 2021). "In addition, in the common carp liver, the KEGG pathway analysis showed that Alzheimer’s disease was related to genes INSR, GAPDHS, BAX, DHCR24, PPARG, ENO1, and VEGFA." (PMID 35741857, 2022). "Consequently, the functional analysis (i.e. based on GO enriched functions) and the molecular structural analysis (i.e. detailed by the BAX-BID interaction) may explain the inverse comorbidity between cancer and Alzheimer’s disease." (PMID 28740175, 2017).
breast tumors (10 papers, 2012 to 2025). "In this study, it was observed that NK cells can upregulate the expression of pro-apoptotic proteins such as C-Caspase 3 and BAX in breast tumor cells, while inhibiting the expression of anti-apoptotic proteins like BCL-2 and BCL-XL." (PMID 38891683, 2024). "BAX pro-apoptotic protein is differentially expressed in breast tumors by the BAX gene." (PMID 34746770, 2021). "BAX, BCL2, NFKB1 and ABCG2 genes expression were compared by using breast tumor tissues on TCGA-BRCA." (PMID 41154846, 2025). "However, only the ECs of cGAMP-treated implanted breast tumours exhibited high expression of pro-apoptotic genes, including CASP3, CASP8, APF1, BID, BAX, and BAK." (PMID 34285232, 2021).